AQP5 (aquaporin 5)
Description:
Aquaporins form homotetrameric transmembrane channels, with each monomer independently mediating water transport across the plasma membrane along its osmotic gradient. Plays an important role in fluid secretion in salivary glands (By similarity). Required for TRPV4 activation by hypotonicity. Together with TRPV4, controls regulatory volume decrease in salivary epithelial cells. Seems to play a redundant role in water transport in the eye, lung and in sweat glands (By similarity).
Synonyms: AQP-5; PPKB
Tractability: Small molecule: a structure with a bound ligand is known; it has a binding pocket of medium quality. Antibody: UniProt places it where antibodies can reach, with high confidence; its Gene Ontology location is reachable by antibodies, with high confidence; UniProt predicts a signal peptide or a membrane-spanning region; the Human Protein Atlas places it where antibodies can reach.
Target class: Ion channel; Other ion channel; Aquaporin; Water-specific aquaporin
Gene: Protein-coding gene on chromosome 12 (49,961,811 to 49,965,682, forward strand). Ensembl gene ENSG00000161798.
Subcellular location: Apical cell membrane; Cell membrane; Cytoplasmic vesicle membrane
Subcellular location (Human Protein Atlas): Plasma membrane
Pathways (Reactome):
Transport of small molecules: Passive transport by Aquaporins
Gene Ontology:
Molecular function: identical protein binding; protein binding; water channel activity; channel activity
Biological process: carbon dioxide transport; cellular hypotonic response; odontogenesis; pancreatic juice secretion; protein homotetramerization; water transport; transmembrane transport
Cellular component: apical plasma membrane; cytoplasmic vesicle membrane; extracellular exosome; plasma membrane; basal plasma membrane; endoplasmic reticulum; membrane; microvillus
Genetic constraint (gnomAD): Loss-of-function variants: 12 observed, 14.77 expected, observed/expected ratio (o/e) 0.81, 90% interval 0.52 to 1.32. The upper end of that interval is the gene's LOEUF score, 1.32, which puts it in group 5 of 6, group 1 being the genes least tolerant of losing a copy. Missense variants: 229 observed, 230.98 expected, observed/expected ratio (o/e) 0.99, 90% interval 0.89 to 1.11. Synonymous variants: 104 observed, 97.37 expected, observed/expected ratio (o/e) 1.07, 90% interval 0.91 to 1.26.
Homologues: Orthologues: chimpanzee AQP5 (100% identical), macaque AQP5 (99% identical), dog AQP2 (95% identical), pig AQP5 (92% identical), guinea pig AQP5 (92% identical), rat Aqp5 (91% identical), mouse Aqp5 (91% identical), tropical clawed frog aqp5 (67% identical), Drosophila melanogaster Drip (37% identical), Drosophila melanogaster Eglp4 (29% identical), Drosophila melanogaster Eglp2 (29% identical), Drosophila melanogaster Eglp3 (29% identical), and 5 more. Paralogues in human: AQP2 (65% identical), AQP6 (53% identical), MIP (53% identical), AQP4 (49% identical), AQP1 (45% identical), AQP8 (29% identical), AQP3 (26% identical), AQP7 (26% identical), AQP9 (25% identical), AQP7B (24% identical), AQP10 (23% identical).
Diseases named in the same sentence as AQP5 in open-access papers:
AQP5 is named in the same sentence as 200 diseases in open-access papers, as found by Europe PMC text mining. Sharing a sentence is not in itself a finding about the gene and the disease. The quoted sentences say what the papers report.
Sjögren’s syndrome (50 papers, 2011 to 2025). "Dysregulation of AQP5 has been associated with various diseases, including Sjögren’s syndrome (SS), bronchitis and cystic fibrosis, stressing the clinical significance for understanding the molecular mechanisms governing AQP5 trafficking and function." (PMID 40241160, 2025). "Downregulation of FoxO1 in the salivary gland in Sjögren’s syndrome causes a direct reduction of AQP5-expressing cells." (PMID 38212454, 2024). "Aberrant expression and localization of AQP5 have been closely linked to the pathogenesis of Sjögren’s syndrome." (PMID 39441465, 2024). "Abnormal AQP5 expression and/or distribution has been associated with some pathophysiological conditions affecting salivary glands including Sjögren’s syndrome, head and neck cancer treated with ionizing radiation therapy, and diabetes." (PMID 37681902, 2023). "Dysfunctional trafficking of AQP5 has been implicated in several human disease states impacting pulmonary function such as Sjögren’s syndrome, bronchitis and cystic fibrosis." (PMID 30555637, 2018). "Dysfunctional trafficking of AQP5 has been implicated in several human disease states, including Sjögren’s syndrome, bronchitis and cystic fibrosis." (PMID 26569106, 2015). "AQP5 dysregulation has been implicated in several disease states, including bronchitis, cystic fibrosis and Sjögren’s syndrome." (PMID 26569106, 2015). "AQP5 has been associated with sicca symptoms in Sjögren’s syndrome (SS)." (PMID 38987432, 2024). "So far, patients- and methodologies-related variabilities may account for the heterogeneity in the detection of anti-AQP5 antibodies among patients suffering from Sjögren’s syndrome and their association with decreased unstimulated saliva flow." (PMID 37681902, 2023). "Indeed, PIP-AQP5 interaction was necessary for proper AQP5 localization in lacrimal glands, and loss of the interaction resulted in abnormal AQP5 localization in a mouse model of Sjögren’s syndrome." (PMID 36768212, 2023). "Previous studies reported that expression of AQP5 decreased in the salivary glands under pathological situations, including in response to radiation, in Sjögren syndrome patients, in diabetes-induced rats, or associated with systemic inflammation after lipopolysaccharide (LPS) stimulation in mice." (PMID 35884950, 2022). "Flavonoid modulation of AQPs has been reported to ameliorate forms of cerebral and retinal edemas of different origins (AQP4), lung injuries (AQP1), and Sjögren syndrome-associated xerostomia (AQP5), to inhibit ovarian tumor growth (AQP5) and protect against UV-induced skin damage (AQP3)." (PMID 29770164, 2018). "Downregulation of GPX4 in salivary gland epithelial cells leads to salivary secretion dysfunction in Sjögren’s syndrome via the lipid ROS/pSTAT4/AQP5 axis." (PMID 40934008, 2025). "Similar to ezrin, prolactin-inducible protein (PIP) can interact with AQP5, controlling its localization in Sjögren’s syndrome patients’ salivary glands." (PMID 39941100, 2025). "Alterations in the expression and function of AQP5 and other aquaporins can lead to a range of pathological conditions, including Sjögren’s syndrome, an autoimmune disease characterized by dry eyes and dry mouth." (PMID 40725460, 2025). "In Sjögren's syndrome, autoantibodies against M3 receptors disrupt AQP5 translocation to the cell membrane, impairing water transport." (PMID 40100646, 2025). "Reduced expression of AQP5 has been measured in patients with Sjögren syndrome, and autoimmune disorder which commonly presents with dryness in the eyes and mouth." (PMID 38756167, 2024). "Anti-AQP5 autoantibodies have been observed in patients with Sjögren’s syndrome who are characterised by dryness of both salivary and lacrimal glands, and they have been implicated in the underlying mechanisms of glandular dysfunction." (PMID 38987432, 2024).
Sjögren’s syndrome (continued). "Defective cellular trafficking and altered distribution of the AQP5 protein were demonstrated in a mouse model of Sjögren syndrome, providing evidence of AQP5 involvement in LG function." (PMID 38771571, 2024). "Research in AQP5 mutant rats, AQP5 knockout mice, and Sjögren’s syndrome patients has demonstrated that abnormal expression of AQP5 leads to decreased salivary secretion and hypertonic and viscous saliva, which induces thirst or dryness in the oral cavity." (PMID 38380102, 2024). "Numerous animal studies and human research data are available regarding the role of AQP5 in experimental autoimmune dacryoadenitis and Sjögren's syndrome." (PMID 38771571, 2024). "The study aims to assess the diagnostic and clinical significance of autoantibodies against aquaporin-1 (anti-AQP1) and aquaporin-5 (anti-AQP5) in primary Sjögren’s syndrome (pSS)." (PMID 39441465, 2024). "Very recently, in a mouse model of Sjögren’s syndrome, anticeramide treatment using myriocin was reported to attenuate inflammation, increase AQP5 expression, and to re-establish salivary gland function." (PMID 37681902, 2023). "In several mouse models of Sjögren’s syndrome, modified AQP5 distribution has indisputably been documented." (PMID 37681902, 2023). "Studies have reported that in patients with Sjögren’s syndrome, AQP5 was rarely labeled at the apical membrane, suggesting a selective defect in AQP5 trafficking in patients with Sjögren’s syndrome." (PMID 37108146, 2023). "Dendrobium candidum extract is a traditional Chinese medicine rich in anthocyanins and can promote the expression of AQP-5 in the exocrine glands of patients with Sjögren’s syndrome." (PMID 37108146, 2023). "According to the results, the mentioned dose was safe and promoted the expression of aquaporin-5 (AQP-5) in the labial glands of patients with Sjögren’s syndrome." (PMID 37396948, 2023). "As observed for PIP, the reduced ezrin expression in salivary glands from Sjögren’s syndrome patients resulted in abnormal AQP5 localization and trafficking." (PMID 36077012, 2022). "Expression of AQP5 is dramatically decreased in lacrimal acinar cells of patients with Sjögren’s syndrome, a chronic autoimmune disease that affects the body’s moisture-producing capacity, including the function of lacrimal and salivary glands." (PMID 35054857, 2022). "The decreased expression of AQP5 levels in Sjögren’s syndrome patients suggests that AQP5 is related to the reduction in tear secretion." (PMID 35054857, 2022). "Decreased AQP5 expression was reported in several illness, including Sjögren’s syndrome, and after radiation." (PMID 35884950, 2022). "Sjogren's syndrome is a chronic autoimmune disorder of the affected glands with lymphocytic infiltration and dysfunction of aquaporin 5 (AQP5)." (PMID 36160715, 2022). "At the functional level, reduced expression of AQP5 has been determined in the lacrimal gland of patients with Sjögren syndrome, an autoimmune pathology characterized by extreme eye dryness." (PMID 34163358, 2021). "Abnormal distributions of ezrin or AQP5 in exocrine gland tissues have been reported in some Sjögren’s syndrome patients." (PMID 34948308, 2021). "Patients with Sjögren’s syndrome (SS) display abnormal AQP5 localization within acinar cells from SGs that correlate with sicca manifestation and glands hypofunction." (PMID 34440877, 2021). "In Sjögren's syndrome, abnormal localization of AQP5 in the lacrimal glands had been reported to contribute to tear loss and dry eye in these patient." (PMID 34540996, 2021). "AQP5 has been detected in salivary exosome secretions and is correlated to patients with diabetes mellitus or Sjögren's syndrome." (PMID 30555637, 2018). "In several pathophysiological conditions, such as Sjögren syndrome, radiation therapy, diabetes, and senescence AQP-5 are reported to be downregulated or with a different localization, all of which correlate with reduced salivary secretion." (PMID 30622434, 2018).
Sjögren’s syndrome (continued). "Actually, the production of saliva in Aqp5 null mutants is reduced by more than 60%, and the polarity of AQP5 has been found to be disturbed in patients with Sjögren’s syndrome." (PMID 28877240, 2017). "The expression/localization of Rab proteins and aquaporin 5 has been shown to be altered in Sjögren's syndrome." (PMID 28348600, 2017). "In patients suffering from Sjögren’s syndrome, an abnormal localization of AQP5, with a predominant basolateral membrane localization instead of an apical membrane localization, and/or an altered AQP5 expression has been observed." (PMID 26828482, 2016). "Similarly, AQP5 interacts with ezrin, forming complexes that are mislocated in the salivary glands of Sjögren’s syndrome patients." (PMID 39941100, 2025). "Moreover, HMGB1 decreased Aqp5 mRNA levels in a mouse model of Sjögren’s syndrome through the activation of the toll-like receptor 4 (TLR4)/NFkB pathway." (PMID 36768212, 2023). "Anti-AQP5 antibodies, recently discovered in blood samples of patients with Sjögren’s syndrome, may also take part in salivary gland dysfunction." (PMID 37681902, 2023). "In addition, the cystic fibrosis transmembrane regulator (CFTR) corrector and potentiator restored AQP5 expression and salivary gland function in a mouse model of Sjögren’s syndrome." (PMID 37681902, 2023). "Furthermore, decreased PIP and Ezrin expression in salivary gland acinar cells from patients suffering from Sjögren’s Syndrome resulted in abnormal AQP5 localization." (PMID 36768212, 2023). "The beneficial effect of Rituximab on unstimulated saliva flow rate was confirmed in a larger cohort of patients with Sjögren’s syndrome, but it remains to assess if this effect may be due to restored AQP5 expression." (PMID 37681902, 2023). "Due to the frequent xerostomia observed in patients with Sjögren’s syndrome, it was hypothesized that altered AQP5 expression and/or localization may account for this observation." (PMID 37681902, 2023). "Overall, abnormal AQP5 localization in salivary glands from patients with Sjögren’s syndrome resulting from multifactorial events may occur in subsets of patients and participate in salivary gland dysfunction." (PMID 37681902, 2023). "Simultaneous downregulation of FoxO1 and Aqp5 mRNA levels in patients with Sjögren’s syndrome may contribute to hyposalivation." (PMID 36768212, 2023). "Indeed, reduced PIP expression in salivary glands from Sjögren’s Syndrome (SS) patients resulted in abnormal AQP5 localization and trafficking to the apical membrane of acinar cells." (PMID 36077012, 2022). "AQP5/ezrin interaction in salivary glands was also reported and this interaction could be involved in the regulation of AQP5 trafficking and may contribute to AQP5-altered localization in Sjögren’s syndrome patients." (PMID 35514349, 2022). "Moreover, our own studies show that the localization of AQP5 in patients with Sjögren's syndrome influences the secretory function of the lacrimal gland." (PMID 34540996, 2021). "The notion of increased function of aquaporin 5 in PPKB is supported by the fact that immunolocalization experiments involving Sjögrens syndrome, which is characterized by hypohidrosis, revealed reduced expression of AQP5 in sweat glands from patients with Sjögrens compared to normal skin." (PMID 27255181, 2016). "Indeed, toll-like receptor activation and TNFα decrease AQP5 expression in salivary glands, while IFN-α (improving xerostomia in patients with Sjögren’s syndrome; increase AQP5 expression." (PMID 26828482, 2016). "Selective defect in aquaporin 5 (AQP5) trafficking is seen in patients with sjogren’s syndrome." (PMID 23272196, 2012). "Many studies have demonstrated that downregulation and abnormal distribution of AQP5 in salivary glands account for disease-associated salivary hypofunction, as observed in Sjögren’s syndrome, following radiation exposure, and in non-obese patients with diabetes." (PMID 34775989, 2021).
Sjögren’s syndrome (continued). "Therefore, we assume that dysregulation of ezrin-mediated AQP5 trafficking to the plasma membrane may be related to exocrine dysfunctions in Sjögren’s syndrome." (PMID 34948308, 2021). "However, in Sjogrens syndrome the tear AQP5 protein is reported to be increased." (PMID 32437405, 2020). "Furthermore, Rituximab (an anti-CD20 monoclonal antibody), which improves xerostomia in patients suffering from Sjögren’s syndrome and induces complete remission of lymphoma in some cases, increased AQP5 expression at the apical membrane of salivary gland acinar cells." (PMID 26828482, 2016). "Cytokines and autoantibodies directed against muscarinic M3 receptors may play a role in the altered distribution and/or expression of AQP5 observed in salivary glands from patients suffering from Sjögren’s syndrome and from animal models of Sjögren’s syndrome." (PMID 26828482, 2016). "Furthermore, in salivary gland biopsies from patients with Sjögren’s syndrome, an autoimmune disease in which the destruction of exocrine glands leads to severe eye and mouth dryness, AQP5 and ezrin were both mislocalized, supporting the importance of ezrin for AQP5 trafficking." (PMID 39062914, 2024). "Further studies are necessary to better understand the role of both AQP5 and AQP1 in xerostomia resulting from Sjögren’s syndrome." (PMID 26828482, 2016). "Although our study did not investigate Sjögren’s syndrome, we observed a similar outcome: AQP-5 levels in group PSP were higher than those in group H, implying that morphological alterations in the LG occur following increased oxidative stress." (PMID 37108146, 2023). "Impaired AQP5 localization was detected or not in the salivary glands of patients with Sjögren’s syndrome." (PMID 37681902, 2023). "There are also data reporting no such alteration in AQP5 expression and distribution in patients suffering from Sjögren’s syndrome." (PMID 26828482, 2016). "However, unlike Sjögren's syndrome, the role of AQP5 in OLP has not been extensively studied, and our findings provide new insights into the potential mechanisms underlying xerostomia in OLP." (PMID 40100646, 2025). "However, other research indicated that the mRNA abundance for AQP-5 was significantly lower in acini of rabbits with Sjögren’s syndrome than in that of rabbits without Sjögren’s syndrome." (PMID 37108146, 2023). "Conversely, an early study described increased AQP5 protein expression in submandibular glands from NOD mice, a well-described mouse model for the study of the autoimmune exocrinopathy that is prevalent in patients with Sjögren’s syndrome, even with a significant decrease in the salivary flow rate." (PMID 35884950, 2022). "AQP5–ezrin complexes were assessed by PLA in hMSG biopsies from patients presenting sicca symptoms but without evidence of autoimmunity suggestive of Sjögren’s syndrome (SICCA-NS; used as control) and patients presenting sicca symptoms and Sjögren’s syndrome (SICCA-SS)." (PMID 34502121, 2021). "In addition, expression of several genes known to be dysregulated in Sjögren's syndrome: CTSS, MHC-II, MMP9, Rab proteins (Rab3D, Rab27A, and Rab27B), IL12α, IFN-γ, TNF-α, and aquaporin 5 (Aq5), and the cholinergic muscarinic M3 receptor (M3R) were quantitatively measured using qPCR." (PMID 28348600, 2017). "Thus, the hypohidrosis observed in Sjögrens syndrome may result from reduced expression of AQP5 and correspondingly, the hyperhidrosis of PPKB may result from an increased function of the gene product." (PMID 27255181, 2016). "Altered AQP5 expression and/or localization could thereby participate to the pathogenesis of Sjögren’s syndrome, even though it could not totally account for saliva impairment." (PMID 26828482, 2016). "While AQP5 was shown to interact through its C-terminal with PIP in normal mouse lacrimal gland, this interaction was lost in mice with Sjögren’s syndrome." (PMID 36077012, 2022).
Sjögren’s syndrome (continued). "For example, the AQP5 C-terminus was found to interact with prolactin-inducible protein (PIP) in control mice (Jcl:ICR, CLEA Japan), but interact with major urinary protein 4 in non-obese diabetic (NOD) mice (model for Sjögren’s syndrome)." (PMID 35514349, 2022).